PIK3CA (phosphatidylinositol-4,5-bisphosphate 3-kinase catalytic subunit alpha)
Diseases named in the same sentence as PIK3CA in open-access papers (continued):
Sharing a sentence is not in itself a finding about the gene and the disease.
head and neck squamous cell carcinoma (73 papers, 2007 to 2026). A squamous cell carcinoma that arises from any of the following anatomic sites: lip and oral cavity, nasal cavity, paranasal sinuses, pharynx, larynx, and salivary glands. "Mutations of the PIK3CA gene are thought to contribute to the development of head and neck squamous cell carcinomas (HNSCC), especially those associated with human papillomavirus infection." (PMID 35267596, 2022). "PIK3CA mutations are believed to contribute to the pathogenesis of human papillomavirus (HPV)-associated head and neck squamous cell carcinomas (HNSCC)." (PMID 35267596, 2022). "While PIK3CA mutations are frequent in head and neck squamous cell carcinomas, mutations involving PIK3CB or PIK3C2B are relatively rare." (PMID 36362284, 2022). "Previous studies indicate that PIK3CA is frequently mutated in human solid tumors like head and neck squamous cell carcinoma, esophageal cancer, squamous cell lung cancer and NSCLC, which suggests its importance in the tumorigenesis of cancers." (PMID 33509213, 2021). "In consistent with our data, abemaciclib and selective PI3K p110α inhibitor combination was superior to single agent treatment in patient-derived xenograft models with PIK3CA mutated head and neck squamous cell carcinoma." (PMID 32899250, 2020). "In head and neck squamous cell carcinoma, it has been shown that the increase in the status of the PIK3CA protein was associated with the progression of lesions from dysplasia to invasive cancer." (PMID 33287350, 2020). "Studies have shown that the overexpression of PIK3CA is associated with the poor clinical prognosis in squamous cell carcinoma of the head and neck (HNSCC)." (PMID 33354413, 2020). "Alterations in PIK3CA, the gene encoding the p110α subunit of phosphatidylinositol 3-kinase (PI3Kα), are frequent in head and neck squamous cell carcinomas." (PMID 28194032, 2017). "We have previously reported high incidence of PIK3CA somatic mutations in head and neck squamous cell carcinoma, particularly in pharyngeal cancers." (PMID 24511546, 2014). "In head and neck squamous cell carcinoma, mutations in PIK3CA were reported in 11% of the cases analysed." (PMID 19384426, 2007). "However, in HPV-ind head and neck squamous cell carcinomas (HNSCs) and anal squamous cell carcinomas, the mutation rate of PIK3CA was significantly lower than that in HPV-asso ones, while in penile carcinoma, the rate was similar." (PMID 38253702, 2024). "When classic real-time PCR was directly compared with ddPCR for the detection of PIK3CA mutations in FFPEs of Head and Neck Squamous Cell Carcinoma patients, it was reported that ddPCR was superior in terms of sensitivity in the PIK3CA mutation assessment in FFPE samples." (PMID 39711963, 2024). "Head and neck squamous cell carcinomas (HNSCC) often harbour PIK3CA mutations but PI3Kα inhibitors can cause some side effects." (PMID 28194032, 2017). "PIK3CA mutations lead to abnormal activation of phosphatidylinositol 3-kinase alpha (PI3Kα), promoting the development of head and neck squamous cell carcinoma (HNSCC)." (PMID 40723456, 2025). "For example, PIK3CA mutations have been observed at lower frequencies in bladder tumors arising in EAS individuals and in head and neck squamous cell carcinomas from AFA individuals." (PMID 38836758, 2024). "A phase Ib/II study (COPAN-ORL06) sponsored by UNICANCER is assessing the MTD, efficacy and RP2D of Copanlisib in combination with Cetuximab in patients with recurrent and/or metastatic head and neck squamous cell carcinoma (HNSCC) with a PIK3CA mutation/amplification and/or a PTEN loss." (PMID 33801659, 2021).
head and neck squamous cell carcinoma (continued). "Accordingly, co‐inhibition of these RTKs using a multi‐kinase inhibitor ponatinib eliminates CSCs and reduces metastasis of PIK3CA‐overexpressing head and neck squamous cell carcinoma cells." (PMID 31600013, 2020). "For head and neck squamous cell carcinomas (HNSCCs) it has been shown by Henderson and colleagues that HPV+ compared to HPV− tumors have elevated APOBEC3B and that PIK3CA helical domain mutations are APOBEC-driven in multiple cancers, including HPV+ HNSCC." (PMID 26097867, 2015). "In low-grade head and neck squamous cell carcinomas PIK3CA was over-represented, as analyzed by CGH or fluorescence in situ hybridization." (PMID 19384426, 2007). "The study of Hippo Yap pathway in head and neck squamous cell carcinoma showed that overexpression of PIK3CA (phosphatidylinositol 3-kinase catalytic subunit α) or the loss of FAT1 (fatty atypical cadherin 1) function could lead to the activation of yap." (PMID 33413358, 2021). "However, gene amplifications of PIK3CA have been studied in head and neck squamous cell carcinomas by Qiu and colleagues." (PMID 28127430, 2017). "In head and neck squamous cell carcinoma, PIK3CA amplification led to earlier recurrence." (PMID 27016421, 2016). "In the colorectal cancer mice model, EphB3 expression was also found to be increased along with tumor development and coamplified with PIK3CA in head and neck squamous cell carcinoma (HNSCC)." (PMID 34959648, 2021). "The results showed that the mRNA and protein expression of GSK3B, PIK3CA, FN1, MET, and SPP1 was significantly upregulated in head and neck squamous cell carcinoma tissues, while MAPK3 was significantly downregulated." (PMID 39323640, 2024). "In head and neck cancers, PIK3CA mutations are one of the most frequent mutations in both HPV-positive and -negative head and neck squamous cell carcinoma (HNSCC) with PIK3CA mutations seen in 21% of HNSCC samples as per the Cancer Genome Atlas program (TCGA)." (PMID 38396649, 2024). "APOBEC activity served as a key driver of PIK3CA mutagenesis and HPV-induced transformation in head and neck squamous cell carcinomas." (PMID 33664766, 2021). "A recent study in head and neck squamous cell carcinomas highlighted that genomic aberrations including EGFR amplifications, AKT1 amplifications and CSMD1 deletions, but not PIK3CA, were highly associated with responsiveness to PI3K-targeted drugs." (PMID 34404439, 2021). "Additionally, PIK3CA and/or EGFR amplification and Rictor overexpression in head and neck squamous cell carcinoma and lung squamous cell carcinoma, and the RICTOR amplification detected in our study are associated with the fact that mTOR inhibitors are under investigation in these tumours." (PMID 37949943, 2023).
metastatic disease (72 papers, 2010 to 2025). "Strong associations emerged between mutations in ESR1, GATA3, and PIK3CA in metastatic tumors, particularly ESR1 mutations at positions 380, 536, 537, and 538 pairing with PIK3CA mutations at positions 542, 545, and 1047." (PMID 40758706, 2025). "In patients with luminal-like phenotype at diagnosis, the most frequently mutated gene during metastatic disease was PIK3CA (39.8%); in those with HER2+ phenotype, ERBB2 was the most frequently altered gene (30%)." (PMID 38473737, 2024). "We aimed to study the discordance rates of PIK3CA mutational status between primary and matched metastatic tumors." (PMID 37392328, 2023). "The aim of this systematic review and study-level meta-analysis was to evaluate the discordance rates of PIK3CA mutational status between primary and matched metastatic tumors in BC patients." (PMID 37392328, 2023). "Conversely, PIK3CA mutations were successfully detected in the plasma-derived ctDNA of patients with metastatic disease with a 95% concordance when analyzed parallel to matching tumor tissue DNA." (PMID 34359713, 2021). "The use of alpelisib in combination with fulvestrant improved progression-free survival in patients with tumors harboring a PIK3CA mutation, which is associated with eventual endocrine resistance that occurs in advanced/metastatic disease." (PMID 32637176, 2020). "We expect based on prior studies that PIK3CA mutation status would have been concordant between primary and metastatic tumors in the same patient, but more data is needed to confirm this." (PMID 32326897, 2020). "We also sequenced paired primary tumor (PT) and metastatic tumor (MT) on two cases (P10 and P12), revealing high concordance of mutations in both tumor specimens from the same patient: PIK3CA H1047R in P10 and PIK3CA E726K in P12." (PMID 32210430, 2020). "The impact of PIK3CA mutation status on BC progression (e.g., localized to metastatic disease) is uncertain." (PMID 32637176, 2020). "Adding PI3K inhibitors to standard endocrine treatment results in improvement of progression-free survival (PFS) in patients with metastatic disease with a PIK3CA-mutated tumor." (PMID 31391067, 2019). "One patient harbored an AKT1 E17K mutation in the recurrent tumor, whereas PIK3CA E542K and E88Q mutations were detected in the primary and untreated metastatic tumor samples." (PMID 30898102, 2019). "The results showed that no statistical differences in the frequencies of EGFR, KRAS, HER2, BRAF, and PIK3CA mutations and other GMs were observed between unpaired primary and metastatic tumors." (PMID 29518290, 2018). "Comparative genomic analyses have identified a high level of concordance particularly for RAS, BRAF, and PIK3CA mutations between colorectal primary and metastatic tumors." (PMID 28178681, 2017). "Of the significant CNA and mutation genes, only PIK3CA mutations frequency varied significantly between primary and metastatic tumors." (PMID 26725848, 2016). "Cases with matched primary and metastatic tumors harbored identical mutations in both sites (PIK3CA/KRAS and RB1 gene mutations, respectively)." (PMID 26625196, 2016). "Regarding the role of PIK3CA mutations in patients with HER2-positive operable or metastatic disease treated with anti-HER2 agents, at present, existing data are inconclusive." (PMID 27129168, 2016). "PIK3CA sequencing showed that two of the seven (29%) patient primary and metastatic tumors and xenografts contained missense mutations." (PMID 24708766, 2014). "PIK3CA mutation status was 90% concordant between primary and metastatic tumors (McNemar P = 0.45), with a prevalence of 33% and 38%, respectively." (PMID 24520381, 2014).
metastatic disease (continued). "Ongoing planned research includes further validation of this method and evaluation of PIK3CA mutational status defined on CTC compared with that of tumor tissue from primary or metastatic disease." (PMID 24670368, 2014). "In this study, PIK3CA mutation was detected in 53% of the metastatic tumors and 45% of the primary tumors, indicating an apparent net gain in PIK3CA mutation in metastatic disease that was thought to be due to heterogeneity in the primary tumor." (PMID 21362200, 2011). "Fresh-frozen research biopsies were therefore obtained from 51 patients with recurrent or metastatic disease for PIK3CA mutation testing." (PMID 21362200, 2011). "Although tumors with PIK3CA mutation had a late recurrence pattern, these mutations were common in metastatic disease and were most often associated with persistent ER expression." (PMID 21362200, 2011). "PIK3CA mutation status may be discordant between primary and metastatic tumor lesions in up to 10% of BC, with most of the discrepancy attributed to the loss of PIK3CA in metastatic tissues." (PMID 40507317, 2025). "Conversely, SK-BR-3 cells, derived from a metastatic tumor, lack PIK3CA mutations." (PMID 41347072, 2025). "Furthermore, Mosele and colleagues recently reported that patients with PIK3CA-mutated metastatic tumors presented with a poor prognosis and resistance to chemotherapy in hormone receptor-positive, HER2-negative metastatic breast cancer." (PMID 33854152, 2021). "Finally we analyzed OS (measured from diagnosis), OS-Ph1 (measured from recorded phase I therapy), and DMFS (measured from diagnosis to metastatic disease) for patients with PIK3CA mutations and wt PIK3CA patients." (PMID 23248156, 2012). "In our research, the distribution of PIK3CA H1047R mutation suggested this mutation might be related to good prognosis in oligo-metastatic disease, whether in oligo-metastasis and poly-metastasis groups, or in oligo-metastasis with longer oligo-R and oligo-metastasis with shorter oligo-R." (PMID 37715134, 2023). "In our study, PIK3CA mutation was more in oligo-metastasis than in poly-metastasis and was also more in oligo-metastasis with longer oligo-R than in shorter oligo-R, suggesting PIK3CA mutation may be related to good prognosis in oligo-metastatic disease." (PMID 37715134, 2023). "In HR+/HER2− BC, PIK3CA has been related to improved clinical outcome in operable primary cases, and to poor prognosis in metastatic disease." (PMID 40507317, 2025). "The average age at diagnosis of metastatic disease was 55 years for PIK3CA-WT patients and 62.4 years for PIK3CA-M patients—figures that align closely with the overall mean ages." (PMID 37761256, 2023). "CTL activity trended to be increased in patients with the neoantigens in RYR3 and DNAH7 in primary tumors and neoantigens in TTN and PIK3CA in recurrent/metastatic tumors." (PMID 33796222, 2021). "The attributes associated with an increased risk of death included higher ECOG performance status, larger tumors, metastatic disease at the time of RT, the presence of portal vein thrombus, the presence of satellite lesions, IDH1 mutation, and PIK3CA mutation." (PMID 34945742, 2021). "Upon multivariable analysis, the factors associated with death included worse performance status, larger tumor, metastatic disease, higher CA 19-9, PVT, satellitosis, and IDH1 and PIK3CA mutations." (PMID 34945742, 2021). "In both datasets, XPO1 mRNA level highly correlated with PIK3CA mRNA, supporting a potential XPO1 targeting in tumors with these clinically relevant genomic mutations found in 30−40% of ER+ metastatic tumors." (PMID 32847042, 2020).
metastatic disease (continued). "Numerous studies have demonstrated the discordance in ER, PR, and HER2 receptor status and other biomarkers, including PTEN and PIK3CA, between the primary and metastatic tumors." (PMID 32695676, 2020). "Case OVA_003 presented three actionable genes, whereby mutated PIK3CA and amplifications in MYC were shared between primary HGSOC and metastatic tumours, but deletions in NFKBIA were specific to the primary tumour." (PMID 32099096, 2020). "We next studied the association of fulvestrant treatment for metastatic disease and ESR1 and PIK3CA mutations." (PMID 30083595, 2018). "The clinical status of the metastatic disease at the time of the plasma collection was strongly linked to the detection of ESR1 and PIK3CA mutations in cfDNA." (PMID 30083595, 2018). "Mutational status between primary and metastatic tumors is highly concordant, but KRAS, HER2, and PIK3CA HS values are significantly higher in metastatic tumors than in primary tumors." (PMID 29518290, 2018). "On the other side, PIK3CA mutations seemed to activate AKT, as expression was higher among mutated primary and metastatic tumors, similar to observations made in colorectal cancer." (PMID 28860563, 2017). "In summary, we generated seven patient-derived orthotopic xenograft models of TNBC that matched original patient primary and metastatic tumors by histology, biomarkers, genomic features and PIK3CA sequencing." (PMID 24708766, 2014). "One of the FC PIK3ca* mice in the control group with a cecal tumor also developed metastatic disease with the spread of cancer to the mesenteric tissue abutting the spleen and pancreas." (PMID 23593290, 2013). "In our case series, about 85% of patients had metastatic disease at the time of PIK3CA testing." (PMID 40507317, 2025). "The transition from favorable to the inferior impact of PIK3CA mutations supported our findings that PIK3CA had a significant negative survival impact at the early stage of metastatic disease and conferred resistance to treatments." (PMID 37344660, 2023). "In our study, PIK3CA H1047R mutation was associated with oligo-metastatic disease, not poly-metastatic disease." (PMID 37715134, 2023). "In these clinical trials, the PIK3CA mutation status of tissue was mainly based on primary and not metastatic tumor samples." (PMID 34453076, 2021). "Patients lacking the PIK3CA mutation in corresponding serum ctDNA all had nonvisceral metastatic disease." (PMID 29689598, 2018). "The frequency of PIK3CA mutations do not change under the pressure of endocrine treatments or the development of endocrine resistance and metastatic disease." (PMID 30083595, 2018). "Four patients with PIK3CA mutations in metastatic tumor tissue had no detectable mutations in their corresponding serum samples, and interestingly, all had nonvisceral metastatic disease." (PMID 29689598, 2018).